LINC01999 (long independently transcribed non-coding RNA 1999)
Gene: Long non-coding RNA gene on chromosome 17 (60,551,138 to 60,596,604, forward strand). Ensembl gene ENSG00000267772.
Diseases named in the same sentence as LINC01999 in open-access papers:
LINC01999 is named in the same sentence as 1 disease in open-access papers, as found by Europe PMC text mining. Sharing a sentence is not in itself a finding about the gene and the disease. The quoted sentences say what the papers report.
cancer (1 paper, 2024). A tumor composed of atypical neoplastic, often pleomorphic cells that invade other tissues. "Genes enriched in DCIS cells from asymmetric lineages included known markers of cancer invasiveness such as CDH245, but also genes with unknown roles in cancer progression, such as DCAF7 and LINC01999." (PMID 38553478, 2024).